CDK4 (cyclin dependent kinase 4)
Diseases named in the same sentence as CDK4 in open-access papers (continued):
Sharing a sentence is not in itself a finding about the gene and the disease.
colorectal cancer (continued). "Generating a model of Palbociclib-resistant RASMUT colorectal cancer cells, we observed an increased expression of p27kip1, cyclin D, CDK4 and CDK6, coupled with an increased association between p27kip1 and CDK4." (PMID 34654798, 2021). "Here, we investigated the role of the CDK inhibitor p27kip1 in the response to the selective CDK4/6-inhibitor Palbociclib, in colorectal cancer." (PMID 34654798, 2021). "Dual blockade of PI3K p110α and CDK4/6 showed synergistic anti-tumor effects in vivo and in vitro in human colorectal cancer cell lines." (PMID 32899250, 2020). "Specifically, CDK4/6 inhibition increases glutamine utilization and sensitivity to glutaminase inhibition in breast and colorectal cancer cells." (PMID 32624705, 2020). "Astragaloside IV significantly inhibits the expression of several key cell cycle-related proteins (Cyclin D1 and CDK4) in colorectal cancer cell lines." (PMID 30832202, 2019). "With the aim of elucidating metabolic adaptive responses and the emergence of potential vulnerabilities consequent to CDK4/6 depletion or inhibition, we targeted CDK4/6 in HCT116 human colorectal carcinoma cells by using specific small interference (si) RNAs." (PMID 28978620, 2017). "Since miR-338 regulated cell growth, cell migration and cell invasion in liver cancer and colorectal carcinoma by targeting CDK4, the role of CDK4 in liver fibrosis remained unclear." (PMID 28095789, 2017). "In the current study, we evaluated the effect of the ethanol extracts from PF on cyclin D1 and CDK4 suppression in the colorectal cancer cells." (PMID 27670681, 2016). "Our results also demonstrated that sAPRIL-BP reduced the expression of CDK4 and cyclin D1 in a dose-dependent manner in the colorectal cancer LOVO cell line." (PMID 25826583, 2015). "Patchouli alcohol which is an important component of Pogostemon cablin EO has been reported to upregulate p21 expression and suppress cyclin D1 and cyclin-dependent kinase 4 (CDK4) expression in colorectal cancer cells with increase in dose." (PMID 25003106, 2014). "In the present study, the therapeutic potential of the selective CDK4/6 inhibitor PD-0332991 in treating colorectal carcinoma was demonstrated." (PMID 24765199, 2014). "Cyclin D1 is known to be a predictive factor for therapeutic response of colorectal carcinoma whereas cyclin D2 is required for the CDK4/6-driven growth of colorectal adenoma cells." (PMID 24765199, 2014). "Disruption of cell cycle regulation through alterations in the Cdk4 pathway appears to play an important role in the development of a variety of cancers including colorectal cancer." (PMID 23530816, 2013). "We conclude that Cdk4 is a potential target for blockade in the chemoprevention of colorectal cancer." (PMID 23530816, 2013). "We had reported that MSP58 regulates colorectal cancer cell proliferation, development, and apoptosis, by the cyclin D1-cyclin-dependent kinase 4-p21 pathway." (PMID 22773039, 2012). "We also reported that MSP58 regulates colorectal cancer cell proliferation, development, and apoptosis, by the cyclin D1-cyclin-dependent kinase 4-p21 pathway." (PMID 22773039, 2012). "We also found that MSP58 regulates colorectal cancer cell proliferation, development, and apoptosis, by the cyclin D1-cyclin-dependent kinase 4-p21 pathway." (PMID 22773039, 2012). "The results showed that in colorectal cancer, the expression of SLC35A2 was positively correlated with the expression of four MYC-associated genes, including MYC, Cyclin dependent kinase 4 (CDK4), Polo like kinase 1 (PLK1), and Pescadillo ribosomal biogenesis factor 1 (PES1)." (PMID 40303483, 2025). "The observed salutary effects of CDK4/6 inhibition on anti-tumor immunity could be the basis for a triple combination regimen associating a CDK4/6 inhibitor, an immune checkpoint inhibitor and a BRD4 inhibitor in colorectal cancer." (PMID 40699853, 2025).
colorectal cancer (continued). "MYC activity is frequently increased in colorectal cancers and therefore may become a useful biomarker of CDK4/6 inhibition prediction if it could be clinically measured." (PMID 40699853, 2025). "Here, we have undertaken an in-depth, unbiased metabolomics approach to assess in greater detail the metabolic reprogramming undergone by HCT116 colorectal cancer cells exposed to either the CDK4/6i Palbociclib, the glutaminase inhibitor Telaglenastat, or their combination." (PMID 40696167, 2025). "Besides, Combined inhibition of both MEK and CDK4/6 is effective in preclinical models of KRAS mutant CRC (Colorectal Cancer) and justifies a planned phase II clinical trial in patients with refractory KRAS-mutant CRC27." (PMID 38600093, 2024). "Aspirin induced human colorectal cancer (CRC) cell apoptosis by suppressing Cyclin D1/CDK4 pathway." (PMID 39161904, 2024). "In terms of the clinical prospects, involucrasin B may serve as an effective treatment option, particularly for colorectal cancer patients with excessive CDK4 activation and aberrant TGFβ signaling pathways." (PMID 38338430, 2024). "In addition, silencing of hsa_circ_000984 down‐regulates the expression of CDK4 by competitively binding with miR‐106b, thus hindering cellular processes in vitro and tumour growth in vivo in colorectal cancer." (PMID 32077624, 2024). "Thus, MCM3AP-AS1 has been suggested to increase CDK4 expression through sequestering miR-545 to arrest colorectal cancer cells at G1 phase." (PMID 35790972, 2022). "Also, decreased levels of uc.77– promote colorectal cancer proliferation by inhibiting FBXW8-mediated CDK4 degradation, while uc.63+ induces gastric cancer progression via NF-κB signaling." (PMID 36214222, 2022). "Since p27kip1 showed variable expression in RASMUT colorectal cancer samples, our study supports the possibility that p27kip1 could serve as biomarker to stratify patients who might benefit from CDK4/6 inhibition, alone or in combination with Src inhibitors." (PMID 34654798, 2021). "For instance, in colorectal cancer, miR-142-3p inhibited CDK4 to restrain cell growth." (PMID 33054738, 2020). "With further detection of G1 phase-related molecule expressions, we found that forced expression of ZFP36L1 or ZFP36L2 markedly reduced cyclin D protein expression but did not change expressions of other molecules, including cyclin A, Cdk2, or Cdk4, in these three types of colorectal cancer cell." (PMID 29426877, 2018). "CDK4 overexpression has been observed in 87 % of human colorectal cancer." (PMID 27670681, 2016). "Furthermore, EOPK significantly decreased proliferation and migration, induced G1-arrest, and inhibited the expression of phospho-ERK, phospho-AKT, β-catenin, cyclin D1 and CDK4/6 in colorectal cancer cells." (PMID 25074784, 2014). "Modification of the Cdk4 pathway using a natural plant-derived compound such as silibinin may be a useful chemopreventive strategy for colorectal carcinomas." (PMID 23530816, 2013). "Briefly, we found that mmu-miR-688 and mmu-miR-30c-1* targeting Tcf712 and Cdk4 are involved in colorectal and pancreatic cancer, respectively, while the same miRNAs targeting Bad, Mapk10, Mapk3 and Tgfbr1 are involved both in pancreatic as well as colorectal cancer." (PMID 22245972, 2012). "Moreover, CDK4/6 inhibitors could downregulate pS6RP in KRAS-mutant colorectal cancers." (PMID 41428766, 2025). "Previous studies showed that orientin can induce G0/G1 cell cycle arrest in human colorectal carcinoma HT29 cells by upregulating the CDK inhibitor p21WAF1/CIP1 and downregulating cyclins D1 and E, as well as CDK2 and CDK4." (PMID 40725115, 2025). "In recent years, combing with MEK and CDK4 inhibitor has more inhibitory proliferation effect for pancreatic ductal adenocarcinoma and RAS mutant colorectal cancer." (PMID 38528618, 2024).
colorectal cancer (continued). "4i induced cell cycle arrest in colorectal carcinoma through downregulating the expression of CDK2, CDK4 and CDK6." (PMID 39487179, 2024). "In colorectal carcinoma COLO205 cells, Tan strongly enhances cell cycle arrest at G1 phase at least in part by diminishing cyclin-dependent kinases 2 (Cdk2) and 4 (Cdk4) activities." (PMID 38924029, 2024). "The silencing of RPS3 reduced cyclin-dependent kinase 4 (CDK4) expression and induced G1 phase arrest in human colorectal cancer cells, which were also observed after treatment with SA." (PMID 36672154, 2023). "This study demonstrated the activity and efficacy of a novel investigational CDK4/6 inhibitor GLR2007 in preclinical models of solid tumors including GBM, and lung, liver, breast, and colorectal cancers." (PMID 36033522, 2022). "In colorectal cancer cells, up-regulation of MCM3AP-AS1 has enhanced expression of CDK4, which is directly targeted by miR-545." (PMID 35790972, 2022). "In colorectal cancer, up-regulation of LINC00467 reduces the expression of cyclin A1, cyclin D1, CDK2, CDK4 and Twist1, and enhances the expression of E-cadherin, thus promoting the development of colorectal cancer." (PMID 34888249, 2021). "Wang and colleagues have recently shown a synergistic inhibition of colorectal cancer (CRC) cell growth through simultaneous inhibition of the EGFR and CDK4/6 pathways." (PMID 33809148, 2021). "In our present studies, dual targeting of CDK1 or CDK4/6 and HSP90 robustly reduced the level of HIF1α and synergistically inhibited cell viability in colorectal cancer lines." (PMID 34686682, 2021). "We investigated the efficacy of the CDK4/6 inhibitor, abemaciclib, and confirmed a synergistic interaction for PI3K p110α and CDK dual inhibition in colorectal cancer cell lines." (PMID 32899250, 2020). "The results revealed that Cyclin D1, Cyclin D2, CDK4 and CDK6 were all decreased in si-SNHG1-transfected colorectal cancer cells." (PMID 30266084, 2018). "Efficacy of the combination of MEK and CDK4/6 inhibitors in vitro and in vivo in KRAS mutant colorectal cancer models." (PMID 27167191, 2016). "The data presented herein have shown that the G1 phase cyclin D1, D2, D3, CDK4, CDK6 and pRB proteins are highly expressed in colorectal carcinoma tissues as compared to the matched adjacent normal colorectal tissues." (PMID 24765199, 2014). "A putative role of the CDK4/6 signaling and the cyclin inhibitor p21 in the immune status of colorectal cancer and the anti-tumor fitness of infiltrating CD4+ T cells was proposed in a study of colorectal cancer in mice." (PMID 40699853, 2025). "More recently, Palbociclib and other CDK4/6 inhibitors (CDK4/6i), in a variety of combinations, have shown efficacy in other cancer types, including colorectal carcinoma, particularly in tumors bearing genetic or epigenetic alterations underlying an upregulated G1-S cell cycle transition." (PMID 40696167, 2025). "CDK4 is found to be amplified in colorectal cancer cells compared to normal cells, and evidence has shown that inhibiting certain CDKs such as CDK1, 2, 4/6, and 9 is useful in enhancing colorectal cancer cell (HCT-116) death." (PMID 37233465, 2023). "By high-throughput i-CR drug screening, they discovered that inhibition of the EGFR and MEK or CDK4/6 pathways exerted a synergistic inhibitory effect against colorectal cancer and supersynergistic effects when EGFR, MEK, and CDK4/6 inhibitors were used simultaneously." (PMID 34150763, 2021). "To further investigate the molecular mechanism of HIF-1α destabilization by CDK1 or CDK4/6 inhibitors, we performed a proteomic screen on immunoprecipitated HIF-1α from hypoxic colorectal cancer cells that were either untreated or treated with CDK1 inhibitor Ro3306 and CDK4/6 inhibitor palbociclib." (PMID 34611473, 2021). "In colorectal cancers, the CDKN2A, CDK4/6, Rb signaling cascade might also control tumourigenesis driven by loss of wild type APC function." (PMID 30655555, 2019).
colorectal cancer (continued). "The aim of this study was to determine whether CDK4, CDK6 and phosphorylated RB proteins were overexpressed in colorectal carcinoma tissues as compared to matched normal colorectal tissues." (PMID 24765199, 2014). "The synergy between TNKS and CDK4 inhibition was not restricted to DLD1 cells, as we observed similar effects of TNKS silencing and Trametinib or Palbociclib treatment in the colorectal carcinoma cell line SW480 (bearing an APC truncating mutation, similar to DLD1)." (PMID 31891587, 2019). "However, whether CDK4 or CDK6 or both were required for RB phosphorylation and G1-S transition in colorectal carcinoma cells remained to be clarified." (PMID 24765199, 2014). "However, it remains unclear whether CDK4, CDK6 or both are required for RB phosphorylation in colorectal carcinoma and thus PD-0332991 can be used to target this CDK-RB axis for the cancer therapy." (PMID 24765199, 2014). "However, whether CDK4, CDK6 or both are required for the G1-S transition of colorectal carcinoma cells remains to be clarified." (PMID 24765199, 2014).
prostate carcinoma (104 papers, 2007 to 2026). A carcinoma that arises from epithelial cells of the prostate gland. "A recent study showed that the inhibitory effect of carvacrol on the cell cycle is associated with the downregulation of cyclinD1 and CDK4 and the upregulation of suppressor protein p21 in androgen-independent PC-3 human prostate cancer." (PMID 37448964, 2023). "miR-193b: miR-193b conferred resistance to CDK4/6 inhibition via downregulation of the cyclin D1-encoding gene (CCND1) in prostate cancer." (PMID 34439268, 2021). "Loss of the CDK4/6 inhibitor, p16INK4a, due to its deletion or reduced expression through promoter hyper-methylation, has been observed in human prostate cancer samples." (PMID 30677079, 2019). "In giant cell carcinoma and prostate carcinoma cells, berberine also decreased G0/G1 phase-associated cyclins (D1, D2, E, Cdk2, Cdk4, and Cdk6), inducing G0/G1 arrest and suppressing cell proliferation." (PMID 23213296, 2012). "Since immunotherapy and CDK4/6 inhibition are currently in clinical trials for prostate cancer with CDK12 mutations, there will be opportunities in future to determine the extent to which CDK12d classification is associated with disease response to various targeted therapies." (PMID 36914848, 2023). "Therefore, our findings not only illustrate the molecular mechanism of BET inhibitor resistance caused by RB loss, but also reveal a potential therapeutic strategy for prostate cancers with abnormalities in RB, CDK4/6, and/or CREB signaling." (PMID 36274096, 2022). "Furthermore, complex promoted dysregulation of several genes that encode CDKs, especially CDK4, a protein commonly overexpressed in prostate cancer." (PMID 34249731, 2021). "Silibinin has been reported to inhibit cell growth and induce G1 arrest in cell cycle progression of human prostate carcinoma, which was associated with decreased levels of cyclin D1, CDK4, and CDK6 and induction of Cip1/p21 and Kip1/p27, followed by increased binding with CDK2." (PMID 28030611, 2016). "Other possible mechanisms underlying prostate cancer resistance to CDK4/6 inhibition that may underpin these results will be explored in detail below and include upregulation of other growth factor pathways such as MAPK and PI3K, CDK2 overexpression, and loss of tumor suppressors such as Rb." (PMID 40075623, 2025). "Prostate cancer patients with RB1 loss may be predisposed to CDK4/6 inhibitor resistance." (PMID 40075623, 2025). "In addition, the Apc-Cdkn1a network also suggests that certain interactions previously associated with other cancer models – such as the SRC-CCND1 functional association found in prostate cancer, or the phosphorylation of CDK4 by SRC in a cell line – are relevant in this model of colon cancer." (PMID 20824133, 2010). "Consistently, prostate cancer cells that acquired resistance to CDK4/6 inhibitors displayed marked TRIP13 overexpression, and functional assays revealed that TRIP13 modulates cellular sensitivity to these agents." (PMID 42099656, 2026). "Prostate cancer cells (LNCaP and PC-3) treated with RV showed reduced expression of cyclins D1 and E, CDK4, and cyclin D1/CDK4 kinase activity." (PMID 40732979, 2025). "This review summarizes the rational and existing clinical data on CDK4/6 inhibitors in prostate cancer." (PMID 40075623, 2025). "Through mediating Rb hypophosphorylation, CDK4/6 inhibitors show in vivo activity in both hormone-sensitive and castration-resistant prostate cancer." (PMID 40519166, 2025). "Studies evaluating CDK4/6 inhibitors in prostate cancer should assess if selective pressure leads to increased RB1 loss and increased small-cell transformation in prostate cancer patients, as this would constitute a significant treatment-related adverse event." (PMID 40075623, 2025). "This study is considered preliminary proof-of-concept and designates CDK4/6 as a valid therapeutic target in prostate cancer." (PMID 41200193, 2025).